MTOR (mechanistic target of rapamycin kinase)
Diseases named in the same sentence as MTOR in open-access papers (continued):
Sharing a sentence is not in itself a finding about the gene and the disease.
cancer (continued). "Pilát (Chaga mushroom) could inhibit cancer cell growth and induce autophagy by increasing AMPK phosphorylation and inhibiting the mTOR signalling pathway in terms of its downstream effectors S6 and S6K1." (PMID 37368660, 2023). "In this present investigation, PI3K/AKT/mTOR signaling was found to be the downstream path of the hsa_circ_0008234/miR-338-3p/ETS1 axis, broadening the regulatory network of PI3K/AKT signaling in cancers." (PMID 37046729, 2023). "Through a diverse set of downstream targets, the PI3K/AKT/mTOR pathway responds to several endogenous or exogenous stimuli to determine EC cell fate and AKT can be catalytically activated by the MLLT11-TRIL complex, which promotes cancer progression." (PMID 37368179, 2023). "In addition, WWTR1 can participate in many cancer cell signaling pathways, such WNT, mTOR and EMT signaling pathway." (PMID 37091799, 2023). "We assessed NPIIAGG and dN/dSPW levels of six major cancer-related pathways which form two strongly connected gene networks: (i) pathways of AKT, mTOR, and EGFR signaling, and (ii) Notch, WNT, and Hedgehog pathways relative to the whole set of 2972 molecular pathways under study." (PMID 37174700, 2023). "In addition, mTOR is among the key regulatory molecules downstream of AKT, and activated mTOR promotes cancer cell proliferation and angiogenesis." (PMID 36835162, 2023). "Notably, in our model, in which cancer cells were treated with mTOR inhibitors, these adapted DNA methylation profiles underwent further changes, which may be partially connected to the antitumour effects of mTOR inhibitors and explain why drug resistance develops rapidly in some cases." (PMID 37088830, 2023). "Moreover, multiple signaling pathways and molecules are involved in the process of proliferation in cancer, including MAPK, ERK, VEGF, PI3K/AKT/mTOR and MMPs." (PMID 37626424, 2023). "Therefore, the investigation of anti-cancer medications that inhibit PI3K and mTOR has emerged as a significant area of research." (PMID 37834269, 2023). "They activate cancer cell signaling pathways and transcription factors, including IGF1/α6β4 complex, FGFR2, TIMP, DNA replication and mTOR signaling, Smad7, KLF4, and TBX2, and downstream proto-oncogenes such as MYC, MET, and CDK1, which facilitate cancer progression." (PMID 37046676, 2023). "Therefore, a deeper understanding of the immunomodulatory effects of PI3K/AKT/mTOR inhibitors may pave the way for their efficient combination with other therapeutic agents, including immune checkpoint blockers, to enhance clinical outcomes for patients with ARID1A‐deficient cancers." (PMID 38041544, 2023). "However, cancer cells can maintain cell proliferation by activating alternative signaling pathways, such as EGFR/ErbB and PI3K/Akt/mTOR, to resist sorafenib-induced apoptosis." (PMID 37296859, 2023). "Beside COL6 ability to modulate the PI3K/AKT pathway in cancer, in vivo and in vitro studies demonstrated an impact of COL6 on such axis in other districts, with also deregulation of MAPK/ERK kinases and upregulation of mTOR in the COL6 knockout context." (PMID 37505240, 2023). "The anti-cancer properties of biguanides are displayed through several mechanisms of action, including the activation AMPK pathway with the consequent inhibition of mTOR and reduction of several pro-tumorigenic effects including cell proliferation and production of inflammatory mediators." (PMID 38146457, 2023). "The action of mTOR on cellular glycolysis includes induction of glucose transporters (GLUTs) such as GLUT-1 and other glycolytic enzymes promoting both cellular glucose uptake and glycolytic flux of cancer cells." (PMID 37786827, 2023).
cancer (continued). "The signaling pathway comprising phosphatidylinositol 3-kinase (PI3K)/AKT/mammalian target of rapamycin (mTOR)/phosphatase and tensin homologue deleted on chromosome ten (PTEN) plays a pivotal role in cancer progression, including cell proliferation and migratory activities." (PMID 36903626, 2023). "Based on observations on the involvement of MIR4435-2HG in MTOR and EMT signaling pathways, we speculate that MIR4435-2HG may mediate interactions between cancer cells and stromal cells by metabolic reprogramming, which may be a future direction for studies." (PMID 37355516, 2023). "Promising cardiac‐specific biomarkers in cancer‐induced cardiac cachexia models and cachectic cancer patients include factors from the TGF‐β family, such as GDF‐15, autophagy markers, such as Beclin‐1, and markers of protein synthesis, such as AKT and mTOR." (PMID 37654192, 2023). "Moreover, siRNA knockdown of PTEN increased PI3Kδ levels and activated AKT/mTOR signaling, while overexpression of PTEN reduced PI3Kδ levels and inhibited AKT/mTOR signaling in cancer cells." (PMID 37670888, 2023). "mTOR is a protein kinase pathway, downstream of the PTEN regulatory cascade, and it controls several interlinked vital cellular regulatory signaling during cancer." (PMID 37602330, 2023). "In this review we highlight the major dysregulations in the PAM signaling pathway in cancer, and discuss the results of PI3K, AKT and mTOR inhibitors as monotherapy and in co-administation with other antineoplastic agents in clinical trials as a strategy for overcoming treatment resistance." (PMID 37596643, 2023). "Indeed, MTOR and MAPK3/1 pathways, among other important cellular processes, can positively regulate protein synthesis, which is required to sustain cancer cell survival and proliferation." (PMID 37511362, 2023). "NMDA is involved in regulating mTOR signaling, which suggests that NDMA might regulate cancer cell growth, division, and invasiveness." (PMID 37566075, 2023). "The GSVA revealed the biological features of CAFs, many cancer-related pathways, such as the adipocytokine signaling pathway, ERBB signaling pathway, GnRH signaling pathway, insulin signaling pathway, mTOR signaling pathway and PPAR signaling pathway are closely associated with CAFs." (PMID 36937411, 2023). "Moreover, taxol drugs inhibit the apoptosis of cancer cells and promote cell proliferation, inhibiting the phosphorylation of PI3K, Akt and mTOR." (PMID 37242569, 2023). "The top 25 KEGG pathways included Cytokine-cytokine receptor interaction, IL-17 signaling pathway, Toll-like receptor signaling pathway, TNF signaling pathway, MAPK signaling pathway, mTOR signaling pathway, NF-κB signaling pathway, JAK-STAT signaling pathway, and Pathways in cancer." (PMID 37381044, 2023). "Also, emerging evidence has demonstrated the interplay between the mTOR and GPX4 signals, modulating autophagy-dependent ferroptosis in several cancer cells." (PMID 38097554, 2023). "The proposed mechanisms through which APOE accelerated cancer is in relation with intracellular adhesion and junctions, thereby decreasing cell contact inhibition and polarizing normal cells to tumor cells through the PI3K/Akt/mTOR pathway." (PMID 38067270, 2023). "PI3K/Akt/mTOR signaling pathway is therefore one of the major alternate pathways through which upstream regulators such as CD147 modulate HIF-1α expression and function resulting in adaptive angiogenesis and metabolic reprogramming exhibited by cancers." (PMID 38023152, 2023).
cancer (continued). "Thus, it promotes efficient anti-tumor responses, cancer cell elimination, and tumor clearance in many cancers, such as breast cancer, through inhibition of the PI3K/AKT/mTOR signaling pathway." (PMID 36835413, 2023). "Further, overactivation of PI3K/Akt/mTOR and the non-canonical NF-κB pathways can also inhibit cancer cell apoptosis." (PMID 37845755, 2023). "However, it has been reported that melatonin induces apoptosis of cancer cells by suppressing PI3K, Akt and mTOR signaling pathways." (PMID 38188676, 2023). "As demonstrated by Rao G, the glycolysis process could be regulated by the PI3K‐modulated AKT1/mTOR axis, thereby accelerating hypoxia‐inducible factor (HIF) activation to enhance angiogenesis and promote glucose uptake in cancer cells." (PMID 37539493, 2023). "Indeed, the inhibition of VEGF/PI3K/mammalian targets of rapamycin (mTOR)/ERK signaling in HUVEC cells decreases angiogenesis, cancer growth, and metastasis." (PMID 36829917, 2023). "In cancer therapy, apigenin modulated PI3K/AKT/mTOR, MAPK/ERK, NF-κB, JAK/STAT, and Wnt/βcatenin signaling pathways PI3K / AKT / mTOR, MAPK / ERK, NF-κB, JAK / catenin, PI3K / AKT / mTOR, MAPK / ERK, NF-κB, JAK / STAT and Wnt / STAT and Wnt / catenin." (PMID 37743502, 2023). "Given the significant roles of the EGFR/PI3K/AKT/mTOR pathway in human cancer, there has been a strong emphasis on investigating its clinical potential by targeting the major components of the EGFR/PI3K/AKT/mTOR signaling pathway using specific small-molecule inhibitors." (PMID 37631344, 2023). "PI3K, mTOR and HER3 receptor, previously discussed as potential biological targets of perhexiline, are recognised sites of action for existing clinically available cancer therapeutics." (PMID 37110858, 2023). "With the improvement of cancer genome profiling technology, a variety of molecular alterations involving both oncogenes and tumor suppressor genes have been described in CCA, and most of the genetic alternations in dCCA involve PI3K/mTOR." (PMID 37193984, 2023). "Besides the well-known targets such as the inhibition of the mTOR signaling pathway, several additional metformin and phenformin targets (e.g., mGPDH, ATF3, STAT3, GSK3, cyclins) have been identified in other cancers." (PMID 38146457, 2023). "Multiple intercellular signaling pathways, such as PI3K/AKT/mTOR, are activated to induce EMT, and lncRNAs have been shown to regulate these intercellular signaling pathways in cancer metastasis." (PMID 37384249, 2023). "Moreover, TSC1/mTOR was found to control RIPK3-dependent necroptosis in intestinal inflammation and cancer." (PMID 38161978, 2023). "Regarding signaling pathways, our findings suggest that morphine may have a role in the activation of the PI3K/AKT/mTOR axis, a dominant signaling pathway in HNSCC as well as in other cancer types." (PMID 36835812, 2023). "Activation of independent proliferation pathways and alterations of downstream targets, such as eIF4E and 4E-BP1, may represent alternative strategies for cancers to acquire resistance to PI3K and mTOR inhibition." (PMID 37642941, 2023). "Resveratrol has been proven that have chemo preventive and chemo therapeutic effects on cancer by acting on NF-κB (nuclear factor kappa-B), Wnt, and PI3K (Phosphatidylinositol 3-kinase)/Akt/mTOR(mammalian target of rapamycin, mTOR), among other pathways, making it a promising anticancer agent." (PMID 37587146, 2023). "The results showed that interfering with TRMT6 could inhibit the proliferation of cancer cells, the number of S phase cells and the protein expressions of p-PI3K, p-AKT and p-mTOR." (PMID 36707905, 2023). "Similarly, LDs in cancer cells are regulated by the sterol regulatory element binding protein (SREBP) and mechanistic target of rapamycin (mTOR)pathways, ultimately becoming the primary energy supply and signalling hub in these cells." (PMID 37997538, 2023).
cancer (continued). "Herein we highlight the biology and biochemistry of the PAM axis, describe its major dysregulations in cancer, show its main crosstalks with other signaling pathways, and discuss PI3K-, AKT-, mTOR-, and PDK1-targeted inhibitors, emphasizing on their mechanisms of therapeutic resistance." (PMID 37596643, 2023). "Furthermore, several signaling pathways, including MAPK, NF-κB, PI3K/AKT/mTOR, and EGFR, are known to be involved in the invasion and migration of cancer cells." (PMID 37626424, 2023). "In addition, we establish the feedback activation of translation of key cancer growth-promoting proteins such as p90-RSK1 and MKNK2 that signals to eIF4E-eIF4A dependent translation following mTOR inhibition." (PMID 36900235, 2023). "AKT1 and mTOR genes had significantly higher expression levels in PDAC cancer samples than in normal samples (*P< 0.01), whereas mTOR expression was not significantly different." (PMID 37503215, 2023). "The KEGG enrichment analysis showed that pathways with the most upregulated DEGs enrichment were pathways in cancer (KEGG: ssc05200), cell cycle (KEGG: ssc04110), microRNAs in cancer (KEGG: ssc05206), mTOR signaling pathway (KEGG: ssc04150), and autophagy-animal (KEGG: ssc04140)." (PMID 37213521, 2023). "The pathway activity analysis revealed a notable contribution of ECM-SRGs to cancer-related pathways, encompassing the cell cycle, apoptosis, PI3K/AKT, RAS/MAPK, RTK, and TSC/mTOR signaling pathways, EMT, hormone AR, and ER, as well as the response to DNA damage." (PMID 37985530, 2023). "No variants were evident in the key cancer genes PTEN, MTOR, AKT1, TSC1/2 or MDM2, or in genes encoding components of PI3K." (PMID 37079639, 2023). "These pathways, such as the PI3K/Akt/mTOR, AMPK, Wnt/β-Catenin, HIF, NF-κB, or MYC pathway, are often dysregulated, resulting in metabolic alterations that facilitate the growth and survival of cancer cells." (PMID 38002335, 2023). "This drug is currently the centre of attraction for development as an anti-cancer agent for many different human cancers, and has demonstrated anInhibition of prenylation-dependent Ras/Raf/MEK and PI3K/Akt/mTOR signalling in lung cancer cells and human lung tumour-associated endothelial cells." (PMID 37193898, 2023). "In this review, we first summarized common cancer related signaling pathways regulated by the HSP70 family proteins such as the RTKs-RAS-RAF-MEK-ERK pathway, the PI3K/AKT/mTOR pathway, and key proteins of other signaling pathways, in a direct or indirect manner." (PMID 37189349, 2023). "mTOR inhibitors (mTORi) have been introduced as an alternative immunosuppressive approach to conventional CNI-based regimens to address both immunosuppression and cancer control." (PMID 37366904, 2023). "In relation to cancer hallmarks and by its connection to HMGB proteins, it is also interesting to mention the importance of yeast studies in the elucidation of the rapamycin signaling pathway (mTOR)." (PMID 37110415, 2023). "In addition to performing protein translation, ribosomes co-regulate cancer cell growth and proliferation through the RAS/RAF/MEK/ERK, MYC, and PI3K/AKT/mTOR pathways." (PMID 37745301, 2023). "Due to the new role of NUAK1 in regulating the Akt signaling and mTOR, we asked whether a combined inhibition of NUAK1 and Akt or mTOR may benefit cancer therapy." (PMID 38135881, 2023). "In addition to the Wnt/β-catenin, Hedgehog, PI3K/Akt/mTOR, and STAT3 pathways, the Notch pathway is another crucial molecular pathway that is prominently active in cancer stem cells." (PMID 37760535, 2023). "It has displayed significant anticancer activity against various types of cancer cells including RCC, and it is hypothesized that dual PI3K/mTOR inhibitor NVP-BEZ235 is a promising antitumor agent against ccRCC." (PMID 38093375, 2023).
cancer (continued). "SGLT2 inhibitors hinder the proliferation of cancer cells and their metabolic reprogramming through a variety of means, including downregulating the Wnt/β-catenin pathway, activating AMPK, inducing ferroptosis, and suppressing mTOR." (PMID 37047011, 2023). "As shown in our results, these genes, especially FARSB, could activate Cell Cycle, DNA Damage Response, Hormone AR pathways, TSC/mTOR and inhibit EMT, Hormone ER, PI3K/AKT, RAS/MAPK, RTK pathways to play a regulatory role in the cancer process." (PMID 37074800, 2023). "For example, in the wing disc, ecdysone functions to regulate the disc size via the mTor pathway, and mutations or hyperactivation of signal transduction pathways such as the PI3K/Akt/mTOR pathway, the Hippo pathway, and the Ras/MAPK pathway are frequently involved in cancer." (PMID 37835534, 2023). "In addition, we identified recurrent CNVs in regions of well-recognized cancer-driving genes (EGFR, MTOR, CCND1, and MYC) or tumor suppressor gene (RB1), with a relatively higher variation in the DN and T stages." (PMID 36914617, 2023). "In addition to anti-cancer activities, GL can modulate oncogenic signaling pathways, such as the PI3K/Akt/mTOR and JAK/STAT5 in cancer." (PMID 37745066, 2023). "mTOR is the major cellular regulator for autophagy which is upregulated during KSHV malignancy, exerting autophagic suppression, which is reported to create metabolically weak cancer cells, making them sensitized against targeted therapy." (PMID 37602330, 2023). "Finally, miR-92a-3p belongs to the miR-17-92 cluster and it has been identified as a biomarker for many human cancers, acting as a tumor-promoting regulator through the PI3K/AKT/mTOR signaling pathway." (PMID 37215481, 2023). "Our group has recently shown that in EG cancer models, the overexpression of FGFR3 and Fibroblast Growth Factor 9 (FGF9) sustains acquired resistance to trastuzumab, through the activation of PI3K/AKT/Mammalian target of the rapamycin (mTOR) signaling pathway." (PMID 36983691, 2023). "Our study and others hold particular significance, especially when considering the weak monotherapeutic activity of mTOR inhibitors (everolimus and sirolimus), which has already been demonstrated in HCC, alongside the efficacy of the vinorelbine in other cancer types." (PMID 38203186, 2023). "Survival meta-analysis showed that NUAK1, Akt isoforms (Akt1, Akt2, and Akt3), mTOR, and Rictor positively correlate with a high hazard ratio (HR) in BRCA, COAD, GBM, PRAD, STAD, and OV, the same types of cancer where NUAK1 correlates with EGFR expression and Akt Ser-473 phosphorylation." (PMID 38135881, 2023). "PCAT6 was highly expressed in various cancers and may activate Wnt, PI3K/Akt/mTOR, and other pathways to regulate cell proliferation and migration; however, the mechanism of action of PCAT6 in HCC is unclear." (PMID 37373132, 2023). "Furthermore, many studies have shown that enhanced cholesterol synthesis can stimulate oncogenic signals, leading to cancer cell growth and proliferation, specifically by activating the PI3K/Akt/mTOR and AMPK signaling pathways." (PMID 37512149, 2023). "The anti-cancer effect of SHK by induction of reactive oxygen species (ROS) has recently drawn attention, modulating cancer survival pathways such as PI3K/AKT/mTOR and MAPKs signaling." (PMID 37107239, 2023). "Thus, in cancer cells, de novo synthesis of purines and pyrimidines is upregulated through various mechanisms, including aberrations in PI3K/Akt/mTOR signaling." (PMID 37958470, 2023). "In cancer, there is an abnormality in the signaling of PI3K/Akt/mTOR due to which many types of research have been done to find the inhibitors of PI3K/Akt/mTOR signaling which may act as anticancer agents." (PMID 36983855, 2023).